FBXW10B (F-box and WD repeat domain containing 10B)
Synonyms: C17orf1; C17orf1A; CDRT1; HREP; SM25H2; C170RF1; FBXW10P1
Tractability: No criterion of Open Targets' tractability assessment is met for any kind of drug.
Gene: Protein-coding gene on chromosome 17 (15,565,484 to 15,619,704, reverse strand). Ensembl gene ENSG00000241322.
Subcellular location (Human Protein Atlas): Nucleoli; Nucleoplasm
Genetic constraint (gnomAD): Loss-of-function variants: 35 observed, 75.09 expected, observed/expected ratio (o/e) 0.47, 90% interval 0.35 to 0.62. The synonymous counts are far from expectation, so gnomAD's model fits this gene poorly and the ratio says little. Missense variants: 570 observed, 889.2 expected, observed/expected ratio (o/e) 0.64, 90% interval 0.6 to 0.69. Synonymous variants: 224 observed, 337.34 expected, observed/expected ratio (o/e) 0.66, 90% interval 0.6 to 0.74.
Homologues: Orthologues: chimpanzee FBXW10B (93% identical), macaque FBXW10B (88% identical), dog FBXW10B (75% identical), mouse Fbxw10 (68% identical), rat Fbxw10 (67% identical), tropical clawed frog cdrt1 (39% identical), zebrafish fbxw10 (24% identical). Paralogues in human: FBXW10 (92% identical).